TRPV4 (transient receptor potential cation channel subfamily V member 4)
Diseases named in the same sentence as TRPV4 in open-access papers (continued):
Sharing a sentence is not in itself a finding about the gene and the disease.
pulmonary fibrosis (continued). "There is limited work on the role of different TRP channels, except for TRPV4, in lung fibroblasts differentiation and lung fibrosis." (PMID 34831281, 2021). "Genetic deletion of TRPV4 was demonstrated to be protective against MI-induced cardiac fibrosis, bleomycin, and D. farina-induced lung fibrosis, supporting such a possibility." (PMID 34831281, 2021). "In airway epithelial cells, TRPV4 activates NF-κB signalling promoting progression of lung fibrosis." (PMID 33395574, 2021). "Previously we reported that TRPV4 plays a role in bleomycin-induced skin and pulmonary fibrosis at histological and biochemical levels." (PMID 33381111, 2020). "Only tissue specific TRP-deficiency will answer the question which cells apart from fibroblasts are responsible for the development of lung fibrosis due to TRPC6 or TRPV4 function." (PMID 30717260, 2019). "In a lung fibrosis mouse model, it has been shown that deletion of TRPV4 protects mice from lung fibrosis." (PMID 31547577, 2019). "Lastly, in pulmonary fibrosis, TRPV4 has been shown to mediate the mechanosensing that drives myofibroblast differentiation and experimental lung fibrosis in mice." (PMID 28523001, 2017). "It has also been shown that blocking TRPV4 activity and Ca2+ influx in lung fibroblasts can effectively block the fibrotic process triggered by mechanical or inflammatory signals and alleviate pulmonary fibrosis in COPD." (PMID 38543079, 2024). "In another study, TRPV4 KO mice were protected from bleomycin-induced pulmonary fibrosis." (PMID 38033335, 2023). "TRPV4 has been found to play a role in regulating pulmonary fibrosis." (PMID 38033335, 2023). "However, the role of TRPV4 mechanotransduction in fibrosis is not fully explored, and the current review discusses the mechanistic role of TRPV4 in cardiac and pulmonary fibrosis." (PMID 34831281, 2021). "Taken together, these findings suggest that TRPV4 regulates TGF-β1/mechanical force-induced fibroblasts differentiation through Rho/NOX4/MRTF-A signaling molecules and identifies TRPV4 as a potential novel therapeutic target for regulating cardiac and pulmonary fibrosis." (PMID 34831281, 2021). "Also, in pulmonary fibrosis, TRPV4 has been shown to mediate the mechano-sensing that drives myofibroblast differentiation and experimental lung fibrosis in mice." (PMID 29354115, 2017). "Our current study identifies a novel TRPV4-TGF-β axis in macrophages that drives myofibroblast differentiation and experimental pulmonary fibrosis through optimal activation of TGF-β." (PMID 41513093, 2026). "It remains possible that the TRPV4 interacting partners are not TLR4-dependent, as other data suggests that TRPV4 interacts with PI3K to mediate pulmonary fibrosis." (PMID 32676078, 2020).
colitis (24 papers, 2011 to 2025). Inflammation of the colon. "Recent data from mouse models of colitis suggest that TRPV4, which is expressed in both vascular endothelial cells and bone marrow-derived macrophages, plays an important role in colitis-associated tumorigenesis." (PMID 38505262, 2024). "Further studies showed that TRPV4 expressed by vascular endothelial cells and potentially macrophages facilitates the progression of colitis-associated cancer induced by azoxymethane/DSS." (PMID 36459135, 2023). "Activation of TRPV4 receptors in the GI tract has a pro-inflammatory effect, and selective blockade of TRPV4 in an animal model of IBD alleviated colitis and the pain associated with intestinal inflammation." (PMID 37402746, 2023). "The activation of TRPV4 in the gastrointestinal tract causes experimental colitis in mice, which also causes the downregulation of claudin-7 and changes in tight junction morphology." (PMID 35028313, 2022). "In animal models of colitis, TRPV4 activation causes inflammation, and its blockade alleviates inflammation." (PMID 32823895, 2020). "Another study showed that TRPV4 is expressed and functional in intestinal epithelial cells; its activation in the GI tract causes increases in intracellular calcium concentrations, chemokine release, and colitis." (PMID 40636716, 2025). "DSS colitis was significantly attenuated in TRPV4-deficient mice compared to wild-type animals." (PMID 38731999, 2024). "Furthermore, it is known that TRPV4 deficiency attenuates colon inflammation by suppressing vascular hyperpermeability in DSS-induced colitis mice." (PMID 34502199, 2021). "Upregulation of TRPV4 has been associated with inflammation in patients with ulcerative colitis and the colitis mouse model, and the TRPV4 channel may potentially increase vascular permeability in colitis inflammation." (PMID 39600697, 2024). "The selective blockade of TRPV4 with its antagonist RN1734 in a TNBS mouse model has been shown to alleviate intestinal inflammation and colitis-associated pain." (PMID 38731999, 2024). "At the same time, intrarectal administration of TRPV4 agonist GSK1016790A exacerbated the severity of DSS colitis." (PMID 38731999, 2024). "Specifically, in a Dextran Sulfate Sodium (DSS) induced colitis model, TRPV4 knockout mice displayed significantly reduced intestinal inflammation compared to their wild-type counterparts." (PMID 37808188, 2023). "Administrations of a selective TRPV4 antagonist RN1734 suppresses the severity of TNBS-induced colitis and visceral pain." (PMID 36459135, 2023). "A previous study indicates that TRPV4 localized in the gastrointestinal tract may play a role in mechanisms of defense in intestinal inflammation and that selective blockade of TRPV4 in animal model alleviates colitis and pain associated with the intestinal inflammation." (PMID 35893357, 2022). "Despite the increased TRPV4 expressions in the colon of both human IBD patients and animal colitis models, the extent of TRPV4 activation to drive human IBD remains largely unexplored." (PMID 34502199, 2021). "TRPV4 agonists have been shown to increase intracellular calcium concentrations and chemokine release in human colon cancer cell lines and induced colitis in mice." (PMID 30365528, 2018). "This inference if supported by the overexpression of TRPV4 in experimental colitis, inflammatory bowel disease and polycystic liver disease." (PMID 21420431, 2011). "Expression of TRPV4 in colonic epithelial cells of mice with experimental colitis is likewise upregulated, while the levels of TRPV4 mRNA in mucosal biopsies taken from patients with inflammatory bowel disease have been found unaltered." (PMID 21420431, 2011). "In keeping with these effects, intraluminal administration of the TRPV4 agonist to the murine colon evokes a transient increase in paracellular permeability and colitis." (PMID 21420431, 2011).
colitis (continued). "TRPV4 in sensory neurons is upregulated in inflammatory bowel disease, and serosal blood vessels in tissues with active colitis are more densely innervated by TRPV4-positive nerve fibers than in biopsies from healthy controls." (PMID 21420431, 2011). "Moreover, the inactivation of TRPV4 channels by capsaicin in experimental colitis suppressed the overactivation of these channels that occurs in colitis." (PMID 37892544, 2023). "Conversely, in other studies, TRPV4 upregulation was associated with the presence of inflammation in UC patients and in colitis model mice, where the TRPV4 channel could increase the vascular permeability in colonic inflammation." (PMID 32455137, 2020). "Furthermore, the expression of TRPV4 in epithelial cells of the colon is significantly enhanced in mice with DSS-induced colitis." (PMID 21420431, 2011). "In addition, deletion of the TRPV4 gene reduces colonic vascular endothelial permeability during dextran sulfate sodium-induced murine colonic inflammation, whereas the up-regulation of TRPV4 results in the progression of colonic inflammation by increasing vascular permeability." (PMID 33981725, 2021). "Therefore, the pro-hypersensitivity function of TRPV4 during colitis is relatively clear." (PMID 32153564, 2020). "For example, the co-involvement of TRPV4 and TRPA1 plays a role in several health conditions, including colitis, itch, respiratory injuries, and chronic cough." (PMID 40325821, 2025). "The search terms used were "Transient Receptor Potential Channels", "TRP channels", "TRPV1", "TRPA1", "TRPV4", "TRPV2", "TRPM2", "TRPM3", "TRPM7", "TRPM8", "TRPC3", "colitis", "inflammatory bowel disease", "IBD", "ulcerative colitis", "Crohn Disease"." (PMID 41096659, 2025). "Other studies using both pharmacological and genetic approaches showed that TRPV4 is upregulated in vascular endothelial cells and contributes to increased vascular permeability promoting DSS-induced colon inflammation." (PMID 36459135, 2023). "Previous study has shown that TRPV4, another family member of TRP channels, is functionally expressed in intestinal epithelial cells, and its activation promotes cytokine release and colitis." (PMID 33251043, 2020). "Conversely, a systemic or local administration of RN1734, a selective TRPV4 antagonist, remarkably relieved the TNBS-induced colitis, suggesting the benefit of attenuating inflammation through blocking TRPV4." (PMID 32153564, 2020). "The administration of TRPV4-selective and non-selective antagonists in a mouse model of colitis significantly reduced macroscopic damage, myeloperoxidase activity, and pain reduction; conversely, TRPV4 agonist treatment yielded opposite results." (PMID 37808188, 2023). "In contrast, the anti-inflammatory action of 5,6-DiHETE directly blocks a polymodal non-selective calcium channel TRPV4, which presumably leads to faster and more potent therapeutic effects against colitis." (PMID 34502199, 2021). "Studies have shown that the activation of TRPV4 by intracolonic administration of agonists in mice acutely induces pro-inflammatory cytokine releases and colon inflammation, whereas pharmacological TRPV4 antagonism abolishes the 2,4,6-trinitrobenzenesulfonic acid (TNBS)-induced colon inflammation." (PMID 34502199, 2021).
ischemia (24 papers, 2012 to 2025). A hypoperfusion of the BLOOD through an organ or tissue caused by a PATHOLOGIC CONSTRICTION or obstruction of its BLOOD VESSELS, or an absence of BLOOD CIRCULATION. "Furthermore, TRPV4 is closely associated with increased vascular permeability in retinal blood vessels, leading to increased retinal edema and ischemia." (PMID 39517820, 2024). "It appears that several channels/transporters can serve as TRPV4 effector proteins and a dual effect of TRPV4 blockage (especially in the acute or delayed phase of ischemia) may be caused by a “switch” between various effectors." (PMID 36568889, 2022). "Besides, involvement of TRPV4 is found in both neuronal and glial pathophysiology associated with ischemia." (PMID 32963700, 2020). "However, TRPV4-mediated currents/Ca2+ entry markedly increased when the neuronal loss was maximal, e.g. 7 days after ischemia, while 1 hour after ischemia the changes were less pronounced." (PMID 22761937, 2012). "The role of TRPV4 in the brain edema formation was reported in the TRPV4–/– animals, where TRPV4 deficiency led to the reduction of cell swelling and amelioration of peri-infarct depolarization, as well as to the decrease in ischemia-induced lesion volume and milder neurological symptoms." (PMID 36568889, 2022). "Moreover, TRPV4 may participate in the pathogenic mechanisms of astroglial reactivity following ischemic insult because it is involved in ischemia-induced calcium entry in reactive astrocytes." (PMID 23459987, 2013). "However, the protective role of TRPV4 in inflammatory injuries associated with ischemia and reperfusion could seem opposite to the pro-inflammatory effects that have been described for TRPV4 activation on neurons or on enterocytes." (PMID 24073272, 2013). "Therefore, TRPV4-mediated calcium entry may be involved in neuronal and glia pathophysiology associated with various disorders of the central nervous system, such as ischemia." (PMID 22761937, 2012). "In our study, we investigated the effect of the deletion of AQP4 and TRPV4 channels on astrocytic volume changes induced by three models of ischemia-mimicking insults." (PMID 38818517, 2024). "Regarding vascular permeability and inflammation, RQ-00317310 is a novel TRPV4 antagonist that shows promising results in retinal edema and ischemia in RVO mice." (PMID 39517820, 2024). "It was previously demonstrated that neuronal TRPV4 channels modulate their excitability and even contribute to glutamate excitotoxicity and strong K+ release from neurons during ischemia." (PMID 38818517, 2024). "On the other hand, TRPV4 channels participate in several cardiac pathological processes such as the development of cardiac fibrosis, hypertrophy, ischemia–reperfusion injuries, heart failure, myocardial infarction and arrhythmia." (PMID 37371124, 2023). "Transient receptor potential (TRP) channels of the vanilloid subfamily, including TRPV1, TRPV2, and TRPV4, are of great interest as they play important roles in ischemia-induced excitotoxicity, inflammation, and apoptosis." (PMID 37108263, 2023). "Pivonkova and co-authors used global TRPV4 knockout to examine the role of this channel in ischemia-induced cerebral edema." (PMID 37108263, 2023). "As observed upon removal of extracellular Ca2+, combined inhibition of NCX, NMDA receptors, and TRPV4 channels during chemical ischemia led to a peak EM of -68.7 ± 3.4 mV (n = 9/9/3, p = 1 × 10−4) and data were affiliated to a single cluster." (PMID 37886111, 2023). "In this study, we demonstrate that both AQP4 and TRPV4 channels, particularly their interaction, play an important role in edema formation after ischemia in vivo and under ischemia-like conditions such as OGD in situ." (PMID 36568889, 2022). "In our previous study, we demonstrated that the lack of either AQP4 or TRPV4 slows down the development of cytotoxic edema in terminal ischemia and TRPV4 deletion attenuates the ECS volume decrease induced by OGD treatment in situ." (PMID 36568889, 2022).
ischemia (continued). "The expression and activity of Trpv4 in the adult rat hippocampus astrocytes was increased after cerebral hypoxia/ischemia in stroke." (PMID 33806707, 2021). "Lastly, as all TRPV channels modulate Ca2+ influx, there is potential for their use in the treatment and prevention of arrhythmias, particularly post-ischemia as described for TRPV4." (PMID 34867442, 2021). "Previous studies have confirmed that TRPV4 is abundantly expressed in the CNS and plays a key role in many CNS diseases, such as ischemia, seizure and epilepsy." (PMID 30455633, 2018). "More experiments will be needed to reveal a possible involvement of TRPV4 activation and MMPs activation in ischemia brain." (PMID 23459987, 2013). "Although we were not able to detect a significant increase in TRPV4-current amplitude in situ following ischemia, intracellular Ca2+ imaging revealed that Ca2+ entry mediated by TRPV4 channels is significantly augmented in astrocytes 1 H and 7D after H/I." (PMID 22761937, 2012). "The role of TRPV4 in astrocyte activation during ischemia was also proposed by Yi and co-authors." (PMID 37108263, 2023). "In a global hypoxia/ischemia rat model, TRPV4 expression rapidly decreased in neurons and gradually increased in astrocytes, suggesting that TRPV4 may participate in neuronal death during the acute phase of stroke and in astrogliosis during the chronic phase." (PMID 36527242, 2023). "Thanks to their wide distribution throughout the brain parenchyma and a broad range of activating stimuli, TRPV4 channels are suspected to contribute to numerous diseases, such as ischemia, glioblastoma, intracerebral hemorrhage, Parkinsonism or even depression." (PMID 37108263, 2023). "Increased TRPV4 expression 1 and 7 days after ischemia coincides with the astrogliosis development." (PMID 37108263, 2023). "The results obtained in this study indicate that the interplay between AQP4 and TRPV4 channels may play a crucial role in the size of early edema development following ischemia." (PMID 36568889, 2022). "Therefore, TRPV4 antagonism is able to inhibit actin stress fibers formation in ischemia, thus preserving/rescuing the integrity of the BBB." (PMID 33806707, 2021). "Furthermore, there is increasing evidence to show that TRPV4 activation in astrocytes during ischemia results in a calcium influx into astrocytes and extracellular accumulation of glutamate, which causes Ca2+ overload of neurons and can trigger neuronal death." (PMID 32963700, 2020). "Marked changes were also observed in the expression of different types of ion channels, such as outwardly and inwardly rectifying K+ channels and chloride channels (ClC2), and moreover, Trpv4 expression almost doubled after ischemia, when comparing the B2 and B3 subpopulations to B1." (PMID 23940528, 2013). "In addition, we found that TRPV4 immunoreactivity increases in hippocampal astrocytes starting 1 hour after ischemia and reaches maximal levels after 7 days of reperfusion." (PMID 22761937, 2012). "We show that TRPV4 expression and activity are up-regulated in astrocytes following ischemia, suggesting that this channel could be involved in the [Ca2+]i elevation occurring in the astroglial syncytium as a result of an ischemic insult." (PMID 22761937, 2012). "Thus, we showed that in AQP4 or TRPV4 knockouts, not only the specific function of these channels is affected, but also the expression of other proteins, which may modulate the ischemic cascade and thus influence the final impact of ischemia." (PMID 38818517, 2024). "Other TRPV4 antagonists, HC-067047, GSK2193874, and GSK2798745, have also demonstrated positive effects in improving retinal edema and ischemia in RVO mice, being able to inhibit the VEGF-induced vascular hyperpermeability." (PMID 39517820, 2024).